CD4 (CD4 molecule)
Diseases named in the same sentence as CD4 in open-access papers (continued):
Sharing a sentence is not in itself a finding about the gene and the disease.
infection (continued). "Infection of B6 mice with H3N2 (A/Switzerland/9715293/2013), coupled with peptide matrix mapping, revealed a likely narrow CD4+ T cell peptide epitope diversity." (PMID 38543915, 2024). "We used bulk RNA-seq to interrogate overall gene signatures in CD4 T cells isolated from the FRT of wild-type and RORγt mutant mice, 17 days post infection." (PMID 38166152, 2024). "Cattle experimentally infected with M. bovis strains show both CD4+ and CD8+ lymphocyte activation during the early stages of infection, as well as IL-17A gene expression that correlates with lung pathology." (PMID 39024223, 2024). "Unexpectedly, we also find that IL-10 drives the differentiation of newly recruited airway effector CD4 and CD8 T cells into tissue resident memory T cells (Trm) after resolution of the infection and has a role in maintaining Trm in the nasal mucosa." (PMID 38950078, 2024). "Both CD4+ and CD8+ T cells can be activated by SAgs via MHC‐II binding, but different activated T cell subsets can influence infection differently depending on the bacterial species." (PMID 39286776, 2024). "We found that the VertX mice reported expression of IL-10 in peritoneal cavity CD4+ and CD8+ T cells, in particular at day 6 post infection." (PMID 39440975, 2024). "The kinetics of the contraction phase differs, at least in part, between CD4+ and CD8+ T cells: CD8+ T cells are progressively reduced starting about 1 month after infection, while the frequency of CD4+ T cells is more stable at least until 2 months." (PMID 39460293, 2024). "As the infection progresses, CXCR4 usage becomes more prevalent, correlating with a more rapid decline in CD4+ T‐cell counts." (PMID 39319247, 2024). "A decrease in the apoptosis of CD3+, CD3+CD4+, CD3+CD8+, and CD3+CD56+ αβ T cells was observed in subjects with a previous natural infection." (PMID 38793803, 2024). "Patients with HAM displayed significantly higher rates of HTLV-1 infection in CD4+CD8+ T cells than AC hPVLs, and there was a similar trend in CD4+CD8dim T cells, which harbored the highest rate of infection of all DP T cell subpopulations." (PMID 38193535, 2024). "In this model, B cell-derived IL-27 is a crucial factor for the survival and function of virus-specific CD4 T cells and TFH cells, enhancing humoral immunity and viral control at the later phase of the infection." (PMID 38966644, 2024). "The absolute numbers of parenchymal CD19+ B cells and both CD4+ and CD8+ T lymphocytes were increased in Cxcl10+/+ mice at day 4 post infection compared to uninfected control mice." (PMID 39803542, 2024). "The regimen utilizing DNA-MOMP as the priming dose followed by CAF01 adjuvanted CTH522 elicited a more balanced CD4/CD8 response and abbreviated the duration of infection." (PMID 39043447, 2024). "Effective clearance of T. pallidum at infection sites involves the induction of a delayed-type hypersensitivity (DTH) response, mediated by CD4+ T cell infiltration and macrophage activation to phagocytose and kill T. pallidum." (PMID 39770782, 2024). "This significance remained after separate adjustments for age, CD4+ T-cell count, CD4+/CD8+ T-cell ratio and recent infection." (PMID 38698440, 2024). "Up to now, knowledge on the induction of spike-specific CD4 and CD8 T cells and on the impact of previous infection on immunogenicity after bivalent vaccination is limited, as most studies have reported aggregated data with small sample sizes." (PMID 38594497, 2024). "In several cases, such as H27R CD4 expressing cells infected with SIVcpz MB897, we found drastic effects where a fully supportive receptor was rendered highly refractory to infection by a single amino acid substitution." (PMID 38014262, 2024). "By day 14pi, the total number of immune cells had decreased to pre-infection values, but CD4+ and CD8+ T-cell percentages remained significantly higher than pre-infection." (PMID 39459849, 2024).
infection (continued). "IL-22-producing CD4+ T cells and ILC3 also play a crucial role in host defenses in the early phases of infection." (PMID 38799550, 2024). "In another study, B cells were detected three weeks after infection with the AP3AS strain of M. gallisepticum in eight-week-old birds and only CD8+ and CD4+ T cells were observed in the first week." (PMID 38474071, 2024). "First, T cells (both CD4+ and CD8+) are activated early in infection in human survivors and persist post-recovery, despite limited antibody responses during illness." (PMID 38164768, 2024). "They observed a primary burst of CD4+ Teff cells in response to EBV, persisting throughout the chronic phase of infection." (PMID 39512353, 2024). "Tregs reduce the CD4 T-cell-dependent cytotoxic CD8 T-cell response to L. monocytogenes, impeding the body’s ability to control infection." (PMID 39483462, 2024). "Immune profiling revealed the correlation between CD4 Tem cells, memory B cells and OBI, enabling a rapid response to infection reactivation through cytokine secretion and antibody production." (PMID 39600945, 2024). "Basal levels of REAF/RPRD2 are higher in hMDMs and human monocyte derived dendritic cells (hMDDCs) than in cycling primary CD4+ T-cells, consistent with a larger role for HIV-1 Vpr in facilitating myeloid lineage cell infection." (PMID 39205287, 2024). "CD4-Foxp3+ and CD4-GZMB+ T cells counts were statically higher at IF region compared to GC in the entire cohort (p˂0.0001) and in each infection status analyzed separately (p˂0.05)." (PMID 38273012, 2024). "The CD4 to CD8 ratio in Group 1 suggested potential autoimmune reactions, while Group 2 indicated potential immunosuppression from severe infection and employing immunosuppressive drugs." (PMID 38468605, 2024). "At day 7 post-infection, when virus-specific T cells are first detected, 40–50% of SARS-CoV-2-specific CD4 and CD8 T cells in the BAL express CD69, and <10% of CD8 T cells co-expressed CD69 and CD103." (PMID 38950078, 2024). "Restimulating mice with S. pneumoniae 6 weeks after primary infection with S. pneumoniae resulted, as expected, an increase in lung CD4+/CD44+/CD62L+ TcM 24 h later, but reduced numbers of CD4+/CD44+/CD62L-/CD27+ effector T cells and their expression of CD103." (PMID 38773113, 2024). "T cell immunity, including CD4+ and CD8+ T cell immunity, is critical to host immune responses to infection." (PMID 38446446, 2024). "First, we measured the changes in the numbers of different immune cells (AMs, monocytes, PMNs, B cells, CD4+ and CD8+ T cells) upon 24-hour infection in the lung by flow cytometry." (PMID 39042472, 2024). "CD4+ and CD8+ T cells were the major intranasal cell populations before infection and increased significantly by day six and fourteen post-infection, respectively." (PMID 39459849, 2024). "Thus, L. infantum-infected moDCs can induce inflammation, drive T-cell chemotaxis, and prime CD4+ T cells following parasite antigen presentation, favoring the development of a cellular immune response against infected cells, which can exert some control over infection." (PMID 38474410, 2024). "To confirm CCR5 as the principal co-receptor used by SIVbn-PBMC s1, we treated baboon CD4 cells with the CCR5 antagonist maraviroc before and during infection." (PMID 39006742, 2024). "Around 7 days post-infection, some remaining clearance was predicted to be attributed to the virus-specific CD8+ response, though the role of virus-specific CD4+ T cells continued to predominate." (PMID 39575237, 2024). "We chose to examine Ire1αΔRorc mice in the acute phases of infection by either Clostridium difficile or Citrobacter rodentium, since ILC3-derived IL-22 is essential to preserve epithelial barrier function, while CD4+ T cells are dispensable at this stage." (PMID 38722686, 2024). "We quantified IL-18R-positive CD4+ and CD8+ T cells in the spleen and peritoneal cavity at 8 days post-infection." (PMID 39446964, 2024).
infection (continued). "Three weeks after infection, once effector T cells were recruited to the lung, groups of mice were treated with mAb to CD4, CD8 or both CD4 and CD8 for two weeks." (PMID 38977711, 2024). "At 60 days post‐infection, the spleen of OM‐TB‐TKO mice contained significantly lower frequencies of CD3+ CD4+ T cells, CD69+ CD4+ T cells, CD25+ CD69+ T cells, PD1+ CD27− T cells, and TIM3+ CD4+ T cells, when compared against O‐TB‐TKO or Y‐TB‐TKO mice." (PMID 39039808, 2024). "The importance of CD4+ memory T cells and cytotoxic CD8+ T cells responding to both infections and vaccinations are discussed and compared." (PMID 38675771, 2024). "After infection, antibody responses to SARS-CoV-2 exhibited a 1,000-fold range in levels, alongside the spectrum of SARS-CoV-2-specific CD4+T cell and CD8+T cell responses." (PMID 39104410, 2024). "We also observed a significant increase in AICD in INH and RIF-treated CD4+ T cells and CD8+ T cells leading to T cell demise and mitigating the adaptive immune response in controlling infection." (PMID 38809023, 2024). "Regulatory T cells, known as Tregs (CD3+CD4+CD25+), exhibited a significant upregulation following infection but showed a notable downregulation after treatment with NAM or AMB." (PMID 38971783, 2024). "In splenocytes, an elevated percentage of T helper CD4+, T cytotoxic CD8+, and NK cells was noted in both WT and TIGIT-KO mice following infection." (PMID 39109867, 2024). "The long-term or permanent expression of anti-HIV genes and the modification of CD4+ and CD34+ cells to render them resistant to infection or to allow the disruption of the HIV life cycle are important strategies in the quest to achieve a HIV cure." (PMID 38474018, 2024). "Two different CD4 T-cell clusters expressing high levels of CCR6+ and S100A4+ appeared late post-infection in young and aged animals, respectively." (PMID 38771046, 2024). "In early infection, M-tropic virus predominates, and mainly uses CCR5 for entry and infection of CCR5+ memory CD4+ T cells." (PMID 39146384, 2024). "Dans le cas de l'infection par le VIH/sida, le VIH va infiltrer un lymphocyte CD4 et y inclure son matériel génétique favorisant la réplication du virus." (PMID 40070975, 2024). "Mouse models show depletion of CD4 and/or CD8 cells reduces viral clearance, and adoptive transfer of Trm CD8+ T cells enhances vial clearance in primary/secondary infections." (PMID 39440808, 2024). "As a result, sex, age, BMI, marital status, infection route, HBV, HCV, CD4, CD4/CD8, time before ART, ART regimens, SMZ-TMP, comorbidities and coinfections were included in the multivariable analysis." (PMID 38287246, 2024). "To investigate the anatomical and temporal distribution of CD4+ and CD8+ T cells following infection, we annotated the T cell compartment in blood and nasopharynx at high resolution into 54 distinct T cell states." (PMID 38898278, 2024). "As the infection persists, the presence of TRM phenotype CD8+ T cells diminishes and is gradually replaced by CD4+ T cells, a shift that signifies a transformation in the immune response during the chronic phase of the infection." (PMID 38469348, 2024). "We also investigated spike-specific CD4+ and CD8+ T-cell responses in a subset of 21 PLWH who experienced their first SARS-CoV-2 breakthrough infection between one and six months after their third vaccine dose." (PMID 38793543, 2024). "While approximately 5% of CD4+ and CD8+ T cells expressed Ki67 at 3 days post-infection, the percent expression increased markedly to 30% at 5 days post-OMP inoculation." (PMID 39440975, 2024). "IFN-γ is one of the main cytokines released during infection by cytotoxic (CD8) and Th1 helper (CD4) T cells, and induces an antiviral state by promoting differentiation and proliferation of T and B cells, and activation of phagocytes." (PMID 39720734, 2024).
infection (continued). "We observed significant downregulation of T cell activation genes in both CD4 and CD8 T cell subsets (r < –0.5, p < 0.008) from pre-infection to day 8 post infection." (PMID 38294906, 2024). "Analysis of adaptive immune cells in the dLNs revealed that the LV-NLRP12 group exhibited a significantly higher count of both CD4+ T cells and CD8+ T cells on the third and seventh days post-infection." (PMID 39119293, 2024). "Specifically, there was enhanced anti-viral CD4 T cell function and improved CD8 T cell function late in infection, suggesting Ptpn22 contributes to the generation of T cell exhaustion." (PMID 38512979, 2024). "Another CTL phenotype (CD4+CD8-) exhibited cytotoxicity towards infected cells at a later phase, 16–24 h after infection." (PMID 38932335, 2024). "Of these, 143 patients (82 (57%) on TNFi monotherapy and 61 (43%) on combination therapy) provided post-vaccination PBMC samples for spike-specific CD4 and CD8 T cell responses 2–4 weeks after up to four SARS-CoV-2 vaccine doses or a breakthrough infection." (PMID 39260039, 2024). "A 2010 study concluded that M. tuberculosis-specific CD4+ T cells were more likely to be infected by HIV, but were also more likely to be depleted during the subsequent course of infection." (PMID 39345793, 2024). "The score incorporates immune (C3 level, IgG level, CD4+ T-cell count, CD8+ T-cell count), and clinical (recipient age, glomerular filtration rate, recipient age, and infection within the first month) variables." (PMID 39660122, 2024). "In the acute phase and convalescent patients, the CD4+ and CD8+ T cells are present in peripheral blood, and their frequency declines during the months after infection resolution and is difficult to detect in chronic hepatitis patients." (PMID 39338957, 2024). "The observation that CD8 Tregs mainly target high affinity CD4 cells suggested that mobilization of CD8 Tregs may allow suppression of robust responses to MHC-disparate tissues without generalized immune suppression and the potential risk of increased vulnerability to pathogenic infection." (PMID 37934601, 2024). "Concerning the histological distribution, CD4+, GZMB+ and Foxp3+ cell counts were higher at the IF region compared to the GC (p˂0.0001) considering the whole cohort and each infection status analyzed separately (p˂0.05)." (PMID 38273012, 2024). "In order to study the contribution of CD4 T cells to Foxp3+ and GZMB+ expression, we analyzed CD4-GZMB+ and CD4-Foxp3+ T cell counts according to the histological distribution, distinct infection status and latency profiles." (PMID 38273012, 2024). "The recent infection testing algorithm (RITA) included a recency assay in blood specimens, viral load, and CD4 cell count prior to antiretroviral treatment use." (PMID 39417513, 2024). "In the present study, vaccine-induced TNF-α+ CD4+ and CD8+ T cell responses to the C protein were higher after vaccination than infection." (PMID 39112523, 2024). "The IgG antibodies against the S protein and IFN-γ- producing CD4+ and CD8+ T lymphocytes are a reliable read-out of humoral and cellular immunity to SARS-CoV-2 following natural infection and vaccination." (PMID 38572317, 2024). "A few months after infection, the EHV-1-specific IFN-γ-producing population shifts from a predominantly CD8+- to a CD4+-T-cell-dominated response." (PMID 39459849, 2024). "In patients with advanced infections, HIV-1 evolves to exploit CXCR4 which correlates with declining CD4+ T cell counts and accelerated progression to AIDS." (PMID 39638817, 2024). "On the other hand, peptides 3–6 showed an elevated subpopulation of CD44+ and IL-2+ within CD4+, and CD3+ populations after 4 days of infection." (PMID 38629077, 2024). "At the 8th week post-infection, in undernutrition 65% + infection group, PD-1, PD-L1, Bax and ICOS were upregulated and CD3+CD4+ and CD3+CD8+ T cell proportions were decreased, while the level of serum IL-10 was increased and IL-12 p70 was decreased." (PMID 38185681, 2024).
infection (continued). "Here, the authors use HLA transgenic mouse models of sequential infections with human coronavirus OC43 and SARSCoV-2 and show that OC43 elicits cross-protective immunity against SARS-CoV-2, which partially depends on CD4 + T cells." (PMID 38278784, 2024). "EBV-specific immune cells differentiated into memory CD4+ (including CD45RA−CD45RO+CCR7− effector memory [EM] and CD45RA−CD45RO+CCR7+ central memory [CM] ~ 0.1%) and CD8+ (2–5%) T cells after infection." (PMID 38280072, 2024). "In contrast to the CD4+ T cell-depleted guinea pigs, α-CD8 and rat IgG treatments had similar effects on guinea pig weight post-infection." (PMID 39495799, 2024). "While not significant, we observed increased IFNγ production by central memory T-cells in group NL4.3 in both CD4 and CD8 T-cells following the boost immunization but prior to infection (W11)." (PMID 38675751, 2024). "As evidence for recent encounter with antigen, spike-specific and SEB-reactive CD4+ and CD8+ T cells from convalescent and infection-naive patients were compared regarding their CTLA-4 expression." (PMID 38326340, 2024). "The strong correlation between CD4 CTL appearance and control of infection with Arm07 suggested an important protective role of this subset in the control of early replication and infection with a virulent virus in previously immunized pigs." (PMID 38675825, 2024). "Only CD4+ T cells infected by CCR5-using M-tropic strains and, to a lesser extent, CCR5-using T/F viruses, which poorly infect macrophages in cell-free infection assays, led to productive infection of the target macrophages." (PMID 38400063, 2024). "Nef function was assessed as the downregulation of cell surface CD4 and MHC-I after infection of SUPT1 cells for 48h with participant-specific Nef PSVs." (PMID 39554110, 2024). "The results shown that, compared to unmodified NPs (TP/PP) and Tri-GalNAc-modified NPs (TP/GP), TP/GPS induced a high numbers of memory CD4+ and CD8+T cells, and offers a certain level of protection against H37Ra strain infection." (PMID 39763671, 2024). "Lentiviruses infected activated CD4+ and CD8+ T cells at the same Multiplicity of infection (MOI), and CD4+ T cells were more likely to express NECTIN-4 TAC and NECTIN-4 TAC28." (PMID 39735536, 2024). "The presence of SARS-CoV-2-responding CD4+ T cells primarily exhibiting a monofunctional profile observed in seronegative children led us to hypothesize that the T cell response might be due to cross-reactivity resulting from prior infection with common circulating endemic HCoVs." (PMID 38235336, 2024). "Accordingly, Sial core-1 O-GalNAc glycans expression remained unchanged through infection in CD8+ cells and slightly increased at 10 dpi in CD4+ cells only." (PMID 39253089, 2024). "Elevated numbers of all subsets of specific immune responses, for instance, those corresponding to MHC-II, IgG, IgA, CD3, CD4, and CD8, have been observed during the subacute stage of infection." (PMID 38400139, 2024). "Activated CD4+ T cells flow into the genital tissue in a CCR5-CCL5-dependent manner, peaking 1 week after infection." (PMID 39207577, 2024). "Macrophages express the entry receptor CD4 and co-receptors CCR5 and CXCR4 which interact with the envelope protein of HIV-1 to facilitate entry and infection." (PMID 39119118, 2024). "In this study, we use these reagents to deplete CD4+ and CD8+ T cells during primary GPCMV infections in male and pregnant guinea pigs and evaluated the role of these T cell populations in controlling infection and congenital transmission." (PMID 39495799, 2024). "Among CD4 T cells, PEP-619WW mice had higher frequencies of TFH and activated/effector-type CD4 T cells during infection than PEP-WT animals." (PMID 38512979, 2024). "Although both CD4+ and CD8+ T cells show polyfunctional responses after primary infection, only the CD8+ polyfunctional subset increases over time." (PMID 39512353, 2024).